TNPO1-DT (TNPO1 divergent transcript)
Synonyms: formerly LINC02056
Gene: Long non-coding RNA gene on chromosome 5 (72,574,098 to 72,816,565, reverse strand). Ensembl gene ENSG00000249085.
Diseases named in the same sentence as TNPO1-DT in open-access papers:
TNPO1-DT is named in the same sentence as 1 disease in open-access papers, as found by Europe PMC text mining. Sharing a sentence is not in itself a finding about the gene and the disease.
TNPO1-DT shares sentences with these, for which no sentence is quoted: glioma (1 paper).